UCP2 (uncoupling protein 2)
Diseases named in the same sentence as UCP2 in open-access papers (continued):
Sharing a sentence is not in itself a finding about the gene and the disease.
Stroke (32 papers, 2007 to 2025). Sudden impairment of blood flow to a part of the brain due to occlusion or rupture of an artery to the brain. "Previous studies from our group highlighted a key role of UCP2 in the predisposition to stroke of the stroke-prone spontaneously hypertensive rat (SHRSP), a suitable model of human disease." (PMID 35629388, 2022). "In our previous studies we found a reduced brain UCP2 expression associated with an up-regulation of the UCP2-targeting miR503 in stroke-prone spontaneously hypertensive rats (SHRSP) exposed to a Japanese style hypersodic diet (JD)." (PMID 32560241, 2020). "The downregulation of uncoupling protein-2 (UCP2) is associated with increased brain and kidney injury in stroke-prone spontaneously hypertensive rats (SHRSP) fed with a Japanese style hypersodic diet (JD)." (PMID 32560241, 2020). "At the time of stroke, rats treated with LV-UCP2 still showed a large UCP2 upregulation in the striatum, associated with increases in OPA1 and FIS1 protein levels, and reductions in PGC1-α, SOD2, TNFα mRNA levels and NRF2 protein levels." (PMID 32560241, 2020). "Our further study demonstrated the mechanisms underlying the protective effect of curcumin on stroke, and found that it is depend on UCP2 mediated anti-oxidant and NO production." (PMID 29490624, 2018). "We explored the potential contribution of UCP2 to the high-salt diet (JD)-dependent increased stroke susceptibility of SHRSP." (PMID 28640254, 2017). "Similar findings were more recently obtained in the brain of the SHRSP, compared to the SHRSR, with evidence of a significant contributory role of reduced UCP2 gene and protein expression in the higher stroke predisposition of the strain." (PMID 29163755, 2017). "Brain UCP2 downregulation is a determinant of increased stroke predisposition in high-salt-fed SHRSP." (PMID 28640254, 2017). "Over-expression of UCP2 in cultured cortical neurons caused 50% less caspase 3 activation, and overexpression in vivo increased resistance to neuronal cell death following stroke and brain trauma." (PMID 19385039, 2009). "However, the injection of a lentiviral vector encoding UCP2 (LV-UCP2) into stroke-prone spontaneously hypertensive rats (SHRSP), fed with a high-salt Japanese-style diet, resulted in the delayed onset of stroke and kidney injury." (PMID 38003681, 2023). "Our study suggests that curcumin exerts a stroke preventive effect by attenuating oxidative stress to improve vascular endothelial function, which might be associated with UCP2 signaling." (PMID 29490624, 2018). "The UCP2 gene downregulation is a key determinant of higher predisposition to renal and cerebrovascular damage in an animal model of spontaneous hypertension and stroke." (PMID 29163755, 2017). "Whether changes in UCP2 expression are associated with development of hypertension and aging and may contribute to the increased incidence of stroke and of other organ damage in SHRSP is currently unknown." (PMID 26023797, 2015). "Notably, the gene encoding UCP2 maps nearby the lod score peak of a Quantitative Trait Locus for stroke (STR1) in SHRSP." (PMID 26023797, 2015). "Interestingly, the gene encoding UCP2 maps nearby the lod score peak of a Quantitative Trait Locus for stroke (STR1) in SHRSP." (PMID 26023797, 2015). "We analyzed the distribution of UCP2 polymorphisms in stroke patients diagnosed with one of the following four stroke subtypes based on the TKM standard pattern identification (PI): Qi-deficiency (QD), Dampness and Phlegm (D&P), Yin-deficiency (YD), and Fire and Heat (F&D)." (PMID 22927880, 2012). "In this study, we showed an association of UCP2 polymorphisms with PI in Korean stroke patients." (PMID 22927880, 2012). "In summary, we demonstrate that UCP2 expression downregulation by high-salt diet associates with increased stroke predisposition whereas UCP2 upregulation, by both nutraceutical and pharmacological agents, associates with a significant stroke protection in high-salt-fed SHRSP." (PMID 28640254, 2017).
Stroke (continued). "For example, in mice, overexpression of human uncoupling protein 2 (UCP2) promoted cortical neuron survival following stroke and traumatic brain injury (TBI)." (PMID 40001492, 2025). "UCP2 overexpression also prevents overproduction of superoxide and oxidative damage in pathological conditions such as stroke and ischemia/reperfusion." (PMID 38292759, 2024). "UCP2 prevents neuronal apoptosis and attenuates brain dysfunction after stroke and traumatic brain injury." (PMID 38568919, 2024). "Ucp2-overexpressing mice demonstrated faster recovery rates after middle cerebral artery occlusion (MCAO)-induced stroke and traumatic brain injury." (PMID 38003681, 2023). "The gene encoding uncoupling protein 2 (UCP2) represents a suitable candidate for the etiopathogenesis of many vascular diseases, including stroke." (PMID 35629388, 2022). "For instance, uncoupling protein 2 (UCP2), a mitochondria membrane protein, has been observed to improve neurological outcomes in stroke." (PMID 35237132, 2022). "UCP2 downregulation upon high-salt feeding favors vascular dysfunction in knock-out mice, and accelerates cerebrovascular and renal damage in the stroke-prone spontaneously hypertensive rat." (PMID 34625529, 2021). "We previously demonstrated that UCP2 is downregulated by ageing and by high-salt feeding in the animal model of stroke-prone spontaneously hypertensive rat (SHRSP), promoting renal and cerebrovascular damage in this model." (PMID 34625529, 2021). "To demonstrate that a single i.c.v. administration could cause a long-lasting overexpression of UCP2, we first performed an immunoblot analysis in the corpus striatum, hippocampus, and cerebral cortex of rats euthanized at the time of the first episode of the stroke." (PMID 32560241, 2020). "We examined the effect of brain-specific UCP2 overexpression on blood pressure (BP), stroke occurrence and kidney damage in JD-fed SHRSP." (PMID 32560241, 2020). "Both substances up-regulated UCP2 and protected JD-fed SHRSP rats against the development of renal and brain damage and susceptibility to stroke." (PMID 32560241, 2020). "We wish to highlight that all measurements were performed in the striatum of rats killed at the first episode of stroke, and, therefore, all changes reflect long-lasting modifications that can be directly or indirectly triggered by UCP2." (PMID 32560241, 2020). "In high salt-treated stroke-prone spontaneously hypertensive rats, UCP2 is downregulated, accompanied by increase of rno-miR-24 and miR-34a, which are known to directly target UCP2 in the kidney." (PMID 30116205, 2018). "More recent study showed that in the brain endothelial cells of stroke prone spontaneous hypertensive rats, microRNA-503 downregulates UCP2, contributing to stroke occurrence in response to high salt diet." (PMID 30116205, 2018). "We recently reported similar findings on UCP2 gene and protein expression with regard to renal damage in the same stroke congenic lines." (PMID 28640254, 2017). "A fundamental demonstration of the role of UCP2 in stroke predisposition of SHRSP was provided by the significant protective impact of BO and fenofibrate administration, both stimulator of UCP2 expression, toward stroke occurrence despite JD feeding." (PMID 28640254, 2017). "In particular, we obtained evidence of reduced UCP2 gene and protein expression in the kidneys of stroke-prone rats and of increased expression in the kidneys of stroke-resistant rats." (PMID 29163755, 2017). "In fact, it was found that UCP2 maps nearby the lod score peak of a quantitative trait locus for stroke (STR1) in the HS-fed stroke-prone spontaneously hypertensive rat (SHRSP), a strain with increased susceptibility to vascular damage." (PMID 29163755, 2017). "Consistently, the administration of JD plus fenofibrate, known to stimulate UCP2 expression, restored brain UCP2 levels, reduced oxidative stress and fully protected from stroke occurrence the high-salt fed SHRSP." (PMID 28640254, 2017).
Stroke (continued). "Male SHRSP, SHRSR, two reciprocal SHRSR/SHRSP-STR1/QTL stroke congenic lines received JD for 4 weeks to detect brain UCP2 gene/protein modulation as compared with regular diet (RD)." (PMID 28640254, 2017). "The administration of BO sprouts extract, another stimulator of UCP2 expression, was also able to delay significantly stroke occurrence in JD-fed SHRSP." (PMID 28640254, 2017). "In this study, we investigated the G-1987A, G-866A, and A55V UCP2 polymorphisms in 586 normal subjects and 1,786 stroke patients diagnosed by two expert TKM doctors using PI, and we thereby elucidated the association of UCP2 polymorphisms with PI." (PMID 22927880, 2012). "Overexpression of UCP2 significantly reduced the IL-6 expression to less than one third of the levels observed in wild-type animals after being challenged with ischemia, suggesting that UCP2 suppresses neuroinflammation in the brain after stroke." (PMID 22348126, 2012). "In the mouse overexpressing human UCP2, brain damage was diminished after experimental stroke and traumatic brain injury, and neurologic recovery was enhanced." (PMID 23029535, 2012). "It has been shown that reduced UCP2 expression is associated with mitochondrial dysfunction, ROS accumulation and increased apoptosis; therefore, UCP2 may be involved in the pathogenesis of neurodegenerative diseases, including stroke." (PMID 37492523, 2023). "On the other hand, UCP2 upregulation could rescue cell viability, reduce vascular damage and stroke occurrence in the high-salt fed SHRSP." (PMID 34625529, 2021). "This strengthens the hypothesis that UCP2 is a key molecular player in central mechanisms of resilience to stroke and might be targeted by therapeutic intervention." (PMID 32560241, 2020). "Uncoupling protein-2 (UCP2) is a mitochondrial endometrial protein that is capable of regulating mitochondrial energy metabolism, decreasing ROS production, and alleviating the neurological impairment and neuronal apoptosis after brain trauma and stroke." (PMID 33101590, 2020). "Because of our experimental design, we could assess UCP2 expression in JD-fed SHRSP rats only at the time of the first episode of stroke, which occurred at different intervals from the onset of JD." (PMID 32560241, 2020). "Increased expression or activation of UCP2 could suppress neuronal damage induced by OS in CNS diseases, such as epilepsy, stroke, and subarachnoid hemorrhage." (PMID 33101590, 2020). "Requirement of neuroprotecting role of UCP2 has already been documented as a prevention of neuronal death and brain dysfunction after stroke and brain trauma and upon UCP2 downregulation by antisense oligonucleotides, which resulted in impaired learning and memory of the mice." (PMID 29351723, 2018). "UCP2 maps nearby the lod score peak of STR1-stroke QTL in the SHRSP rat strain." (PMID 28640254, 2017). "Our data strengthen the role of UCP2 as a suitable therapeutic target for stroke." (PMID 28640254, 2017). "Importantly, both treatments, by their ability to restore regular levels of both microRNA-503 and UCP2, significantly protected from stroke occurrence the JD-fed SHRSP." (PMID 28640254, 2017). "Next, based on knowledge that fenofibrate and Brassica Oleracea (BO) stimulate UCP2 expression through PPARα activation, we monitored stroke occurrence in SHRSP receiving JD plus fenofibrate versus vehicle, JD plus BO juice versus BO juice plus PPARα inhibitor." (PMID 28640254, 2017). "As observed at the end of 4 weeks of the combined treatment, the concomitant administration of JD and BO restored UCP2 level, decreased levels of both NF-κB and oxidative stress despite JD, and led to a significant delay of stroke occurrence." (PMID 28640254, 2017). "Moreover, in mice overexpressing human UCP-2 gene, brain damage was diminished after experimental stroke and traumatic brain injury, and neurological recovery was enhanced." (PMID 22849356, 2012).
Stroke (continued). "Thus we speculate that UCP2 signaling is involved in the preventive effect of curcumin on stroke in hypertension via the decreasing ROS and increasing NO levels." (PMID 29490624, 2018). "Thus, Sesn2 provides useful indirect evidence of the beneficial role of UCP2 in stroke." (PMID 29163755, 2017). "High-salt diet fed SHRSP showed a significant upregulation of brain miR-503 level compared to the control strain, the stroke resistant spontaneously hypertensive rat (SHRSR), with a consequent decrease of brain UCP2 expression and increased stroke occurrence." (PMID 31941075, 2020). "This approach allowed us to demonstrate, for the first time, that selective UCP2 overexpression in the corpus striatum protects JD-fed SHRSP rats against renal damage and delays stroke occurrence." (PMID 32560241, 2020). "15, 16, 17, 18, 19, 20, 21 We previously reported an age-related spontaneous decrease of UCP2 gene and protein expression only in the brain of SHRSP, preceding spontaneous stroke occurrence at 1 year of age." (PMID 28640254, 2017). "Both fenofibrate and BO significantly decreased brain microRNA-503 level, upregulated UCP2 expression and protected SHRSP from stroke occurrence." (PMID 28640254, 2017). "Accordingly, a SHRSR-derived stroke congenic line, carrying a fragment of the SHRSP-STR1/QTL (containing UCP2), showed brain UCP2 downregulation under JD feeding associated with increased inflammation and oxidative stress." (PMID 28640254, 2017). "We discovered a differential regulation of UCP2 expression levels, upon the stroke-permissive high salt diet, in kidneys of SHRSP versus SHRSR with evidence of reduced expression in stroke-prone and increased expression in stroke-resistant rats." (PMID 27594970, 2016). "Furthermore, although the SAH stroke may stimulate the UCP-2 increase by a feedback regulation mechanism, the irisin treatment enhanced this promotion of UCP-2 in the SAH + irisin group." (PMID 33613273, 2021). "Interestingly, we previously demonstrated that high-salt diet suppressed UCP2 expression in both kidney and brain of high-salt fed SHRSP, and that upregulation of UCP2 could prevent both renal injury and stroke occurrence in this model." (PMID 34625529, 2021). "The uncoupling abilities of UCP2–5 appear to be moderate; their mild mitochondrial uncoupling could avoid excessive mitochondrial reactive oxygen species (ROS) production, thus reducing cellular oxidative damage, as recently proved for UCP2 and UCP3 in stroke and ischemia/reperfusion." (PMID 32842667, 2020). "However, a direct evidence that UCP2 is protective in this stroke model is still lacking." (PMID 32560241, 2020). "For ethical reasons, we did not examine whether brain UCP2 overexpression could prolong the lifespan of JD-fed SHRSP rats, and all animals where euthanized at the time of the first episode of stroke." (PMID 32560241, 2020).
Insulin resistance (27 papers, 2003 to 2025). Increased resistance towards insulin, that is, diminished effectiveness of insulin in reducing blood glucose levels. "Moreover, they also observed an association between UCP2-866G/A polymorphism and insulin resistance among 5781 middle-aged Danes and 377 young health Danes, where subjects carrying the G allele consistently had lower insulin sensitivity." (PMID 24804925, 2014). "However, telomere length variation has been also associated with insulin resistance, oxidative stress, and uncoupling protein 2 (UCP2), all of which one related to fat metabolism." (PMID 21791083, 2011). "PGC-1α regulates UCP2 protein expression and this protein plays an important role in the regulation of energy metabolism restoring glucose intolerance and insulin resistance." (PMID 31937343, 2020). "Our results suggest that insulin or moderate hyperinsulinemia in response to insulin resistance induces UCP-2 expression in ECs and VSMCs or in the aorta from BATIRKO MH mice respectively." (PMID 25077985, 2014). "Additionally, UCP2 influences mitochondrial function and reactive oxygen species production, further impacting cellular metabolism and insulin resistance." (PMID 39707176, 2024). "It probably could prevent insulin resistance in early stage by classifying the genotype of rs649446 and rs7109266 in UCP2." (PMID 29849618, 2018). "Moreover, it has been demonstrated that UCP2 is upregulated in response to different pathological states such as insulin resistance, inflammation, oxidative stress, and high levels of FFA, which are all features of MetS." (PMID 27399675, 2016). "UCP-2 may act as an important regulator of energy and lipid metabolism, insulin resistance, glucose utilization, and regulation of reactive oxygen species." (PMID 24312343, 2013). "Furthermore, UCP2 down-regulation also improves insulin resistance in white adipose tissue." (PMID 32854204, 2020). "Moreover, TNF-α may directly downregulates adiponectin contributing to the development of vascular insulin resistance and the decrease of UCP-2 levels in the aorta." (PMID 25077985, 2014). "As insulin resistance (IR) is an established risk factor for colorectal cancer (CRC), we explored the association between each of the IR-related gene polymorphisms of adiponectin (ADIPOQ) rs2241766, uncoupling protein 2 (UCP2) rs659366, and fatty acid-binding protein (FABP2) rs1799883 and CRC risk." (PMID 23826253, 2013). "Our data suggest that moderate hyperinsulinemia in response to insulin resistance or lowering of TNF-α levels within the aorta attenuates vascular damage, this protective effect being mediated by UCP-2 expression levels through iNOS." (PMID 25077985, 2014). "Moreover, another mitochondrial protein called uncoupling protein-2 (UCP-2) plays a pivotal role in the optimal mitochondrial function and thermogenesis, and this way it can affect body weight and insulin resistance as well." (PMID 38678284, 2024). "These actions were parallel to reduced insulin resistance, improved mitochondrial respiration, mitochondrial oxidative capacity, and fatty acid oxidation, with effective regulation of prominent energy regulation markers such as AMPK, Pparα, and UCP2." (PMID 34068459, 2021). "In PAI-1-/- mice, increased skeletal muscle UCP-2 and UCP-3 may contribute to increased metabolic rates and energy expenditure, leading to protection against insulin resistance." (PMID 29163785, 2017). "Thus, moderate hyperinsulinemia in response to insulin resistance or lowering of TNF-α levels within the aorta attenuates vascular damage, this protective effect being mediated by UCP-2 expression levels through iNOS." (PMID 25077985, 2014).